EZH2 (enhancer of zeste 2 polycomb repressive complex 2 subunit)
Diseases named in the same sentence as EZH2 in open-access papers (continued):
Sharing a sentence is not in itself a finding about the gene and the disease.
cancer (continued). "The highest frequency genes in CNGs, BIRC5, ERBB2 and EZH2 were used to perform a pan-cancer mutational analysis." (PMID 29459674, 2018). "KDM6B seems to prevent some neurodegenerative diseases, such as Alzheimer’s disease, but the most documented disease linked to KDM6B and EZH2 dysregulation is cancer." (PMID 34991274, 2018). "Recent studies have shown that somatic mutations in EZH2 gene are observed in specific cancer types." (PMID 29556394, 2018). "Deregulation of EZH2 is frequently observed in a variety of cancers and is associated with cancer initiation, development, progression, metastasis and drug resistance." (PMID 29864144, 2018). "Later two anticancer drugs were reported that target EZH2, both inhibit EZH2 carrying a cancer-specific mutation." (PMID 30344952, 2018). "EZH2 (Enhancer of Zeste Homolog-2) is another chromatin remodeler implicated in cancer resistance to chemotherapy." (PMID 29988316, 2018). "As expected, hypermethylated CpGs in aging and cancer were associated in all tissues with the presence of EZH2 and SUZ12, components of the polycomb complex which directly deposits the H3K27me3 mark." (PMID 29504244, 2018). "Previous studies have demonstrated that the let-7c—EZH2 axis is associated with migration and invasion abilities in cancer cells." (PMID 29445149, 2018). "Unopposed EZH2 activity is also a driver of cancers determined by the loss of the core subunit SNF5/SMARCB1 in the SWI/SNF complex as demonstrated in rhabdoid tumor, a highly malignant aggressive type of pediatric cancer." (PMID 30510924, 2018). "The reader must keep in mind that EZH2 inhibitors are useless or even harmful in those cancers characterized by a loss of function of EZH2." (PMID 30510924, 2018). "Multiple EZH2 target genes were identified and their repression by EZH2 was associated with cancer aggressiveness." (PMID 29864144, 2018). "EZH2 has been widely studied as a protein implicated in cancer and metastatic progression and its upregulation is linked to an aggressive phenotype and to enhanced proliferation by cancer cells." (PMID 28195240, 2017). "Our data are consistent with previous findings that, in cancer cells, EZH2 mediates genes implicated in immunity, inflammation, and angiogenesis." (PMID 28088786, 2017). "EZH2 is highly expressed in a wide range of cancer types and has been implicated in the progression and metastasis of hepatocellular carcinoma, bladder cancer and melanoma." (PMID 28620234, 2017). "Previous studies have shown that EZH2 is a master regulator for cancer stemness, and that EZH2 expression is associated with increased metastatic potential, as well as poor clinical outcome in RCC patients." (PMID 28978010, 2017). "EZH2 overexpression has been reported in several types of cancer and is associated with adverse outcomes." (PMID 28261562, 2017). "EZH2 is highly expressed in several cancer types including NPC and associated with the expression of several target genes involving in growth, metastasis and prognosis of cancers." (PMID 28360411, 2017). "Various cancers have displayed overexpression of EZH2 and it has been associated as a marker for malignancy potential and poor clinical prognosis, including HPV-positive OPSCC." (PMID 28143553, 2017). "Several therapeutic targets in ARID1A mutated cancers are in development, including EZH2 inhibitors." (PMID 29093822, 2017). "EZH2 is recurrently mutated in many types of cancer and play an important role in cancer proliferation and progression." (PMID 29212262, 2017). "In most cases, high EZH2 expression is associated with metastasis and advanced disease in each of these cancer types." (PMID 28410242, 2017).
cancer (continued). "EZH2 is a member of Polycomb-group (PcG) family and associated with transcriptional repression and cancer development." (PMID 29212262, 2017). "Overexpression of EZH2 has frequently been associated with increased tumor aggression and poor clinical outcomes, as well as a potential role in the formation of cancer stem cells." (PMID 28878842, 2017). "A wide spectrum of genetic as well as epigenetic aberrations are associated with cancer development, many of which are associated with histone methyltransferase EZH2 dysregulation." (PMID 29141691, 2017). "The study revealed that loss of function of EZH2 by NOTCH1 activation promotes cancer progression of T-ALL." (PMID 28561778, 2017). "The EZH2 histone methyltransferase is a member of the polycomb repressive complex 2 (PRC2) that is highly expressed in diverse human cancers and is associated with a poor prognosis." (PMID 28785086, 2017). "This review will synthesize the molecular carcinogenesis of these malignancies and their unique clinical behavior, as a foundation for an emerging frontier of targeted therapeutics – the synergistic inhibition of EZH2 in ARID1A mutated cancers." (PMID 29093822, 2017). "EZH2 is frequently overexpressed or mutated in breast, prostate lung and other cancers, and inhibitors targeting EZH2 are currently being examined as a therapeutic approach to treat these tumors." (PMID 28445939, 2017). "Various oncogenic transcription factors and cancer-associated non-coding RNAs including microRNA regulate EZH2 expression." (PMID 28147317, 2017). "Overexpression of enhancer of zeste homolog 2 (EZH2) is associated with different types of cancer and it has been studied that EZH2 catalyzes histone H3-K27 triMe." (PMID 28401148, 2017). "Liu and colleagues have described how EZH2 represses the expression of miR-622 which is an important negative regulator of the chemokine receptor CXCR4 that is implicated in multiple steps of cancer development." (PMID 29079534, 2017). "EZH2 has emerged as a highly attractive target based on its elevated expression in human carcinomas and association with poor clinical outcomes." (PMID 28785086, 2017). "The present studies demonstrate that targeting MUC1-C in carcinoma cells is associated with downregulation of EZH2, SUZ12 and EED expression, indicating that MUC1-C activates major components of the PRC2 complex." (PMID 28785086, 2017). "Deregulation of EZH2 has been documented in various cancer types, both solid and hematological, and is associated with poor survival." (PMID 27449082, 2016). "While SUZ12 and EED mutations have only been found to have loss-of-function effects, EZH2 mutations have been found to have both activating and inactivating functions in different cancers." (PMID 27471434, 2016). "Upregulation of EZH2 levels has been associated with several cancers promoting tumorigenesis partly through the silencing of critical target genes." (PMID 27764181, 2016). "Expression of EZH2 has been found to be associated with poor prognosis and increased in metastasis in different cancers as reported by previous studies." (PMID 27223261, 2016). "EZH2 has been particularly associated with the expansion of cancer stem cells, cell cycle progression, accumulation of DNA damage through inhibition of DNA damage repair and epithelial to mesenchymal transition." (PMID 27793053, 2016). "For miR-101, it was proposed that the loss of it lead to overexpression of EZH2 and cancer progression in further." (PMID 27447860, 2016). "Various oncogenic transcription factors and cancer-associated non-coding RNAs regulate EZH2 expression." (PMID 26871294, 2016). "Increasing evidence indicates that EZH2 is associated with a number of cancers, including nasopharyngeal esophageal cancer, breast cancer, lung cancer and bladder cancer." (PMID 27706111, 2016). "Functional analysis was performed to identify the association between EZH2 and miR-31 using cancer cell lines." (PMID 26871294, 2016).
cancer (continued). "Although EZH2 is considered a functional oncogene, and strongly associated with the progression and invasion of certain cancers, the role of EZH2 in lipid metabolism has been seldom reported." (PMID 27936205, 2016). "Various mutations and abnormal expression of EZH2, the major enzyme catalyzing H3K27me3, are associated with cancers." (PMID 27034728, 2016). "Through its effects in the epigenetic regulation of critical genes, EZH2 has been strongly linked to cell cycle progression, stem cell pluripotency, and cancer biology, being currently at the cutting edge of research." (PMID 27199994, 2016). "With more and more research available, the epigenetic molecule EZH2 is regarded as a transcriptional repressor associated with many cancer types." (PMID 27706111, 2016). "In cancer, EZH2 hyperactivity can be caused by activating EZH2 gene mutations or overexpression due to defective regulation." (PMID 27191993, 2016). "On the other hand, the findings that EZH2 enhances the epithelial characteristics of OC cells argue against the concept that this HMT is an oncogene associated with cancer metastasis." (PMID 27563817, 2016). "Many studies have shown that the overexpression of EZH2 in human cancers is often associated with poor prognosis." (PMID 27471434, 2016). "The gene of EZH2, encoding a polycomb group protein, plays an important role in tumorigenesis and cancer progression through epigenetic gene silencing and chromatin remodeling." (PMID 26754405, 2016). "Evidence suggests that overexpression of EZH2 is strongly associated with cancer progression and poor outcome in disparate cancers, including hematologic and epithelial malignancies." (PMID 27784285, 2016). "A recent model suggests that EZH2 inactivating mutations contribute to cancer stem cell development through the induction of HOXA9 expression, thus supporting myeloid progenitor self-renewal." (PMID 26497210, 2016). "Through its implications in the epigenetic regulation of critical genes, EZH2 has been strongly linked to cell cycle progression, stem cell pluripotency, and cancer biology being currently at the cutting edge of research." (PMID 27199994, 2016). "Increased and decreased expression of EZH2 have both been implicated in the development and progression of a variety of cancers types." (PMID 27449082, 2016). "For example, microRNAs like miR-101, miR-205 and miR-26a regulate chromatin modifiers in cancer such as the Polycomb associated histone methyltransferase EZH2." (PMID 26983574, 2016). "Evidences suggest that overexpression of EZH2 is highly associated with cancer progression and outcome in different cancers." (PMID 26872811, 2016). "The proposed model of EZH2 “loss of function” mutations (of which the majority were found in the SET domain) attributes their contribution to be forming cancer stem cells, via HOXA9 mediated self-renewal of myeloid progenitors." (PMID 27239242, 2016). "Of note is that the SAM competitive inhibitors are effective against cell lines bearing gain-of-function EZH2-mutations (Tyr641 or Ala677), even if they induce a decrease of H3K27me3 in both EZH2-mutated and wild-type cancer cells." (PMID 27222667, 2016). "The oncogenic potential of EZH2 coupled with the fact that widespread epigenetic deregulation is a hallmark of cancer implicates EZH2 as an important driver of cancer development and progression." (PMID 26871474, 2016). "Previous studies have shown that increased EZH2 is involved in the pathology of gastrointestinal inflammation and associated cancers." (PMID 27938379, 2016). "Other polycomb group (PcG) proteins besides EZH2 have oncogenic potential, while proteins counteracting PcG function e.g. the Trithorax group (TrxG) proteins are often implicated in cancer." (PMID 27191993, 2016). "We sorted each grade of carcinomas according to the expression level of EZH2 to clarify the association between grade of malignancy and EZH2 expression." (PMID 27502594, 2016).
cancer (continued). "A recent paper identified a synthetic lethal interaction between EZH2 and ARID1A in ARID1A-mutated cancers, thus providing therapeutic opportunities since EZH2 can be pharmacologically targeted." (PMID 26579514, 2015). "The association between EZH2 expression and OS was reported in 40 studies enrolling 5,737 patients with various cancer types." (PMID 25974088, 2015). "Among the upregulated genes were those encoding well-known enzymes such as EZH2, a histone methyltransferase catalyzing H3K27me3, and which has already been identified as a potential therapy target for cancer." (PMID 26169266, 2015). "This study aimed to assess the prognostic significance of EZH2 expression in cancer survival by exploring the association between EZH2, various survival measures, and clinicopathological features of various cancer types." (PMID 25974088, 2015). "High expression of the histone methyltransferase (HKMT) EZH2, in some cases associated with gene amplification, has been well documented in a variety of cancers." (PMID 26300989, 2015). "In future studies, we can additionally investigate the prognostic significance of EZH2 single-nucleotide polymorphisms for cancer survival." (PMID 25974088, 2015). "EZH2 is considered an oncogene due to its overexpression in many different types of cancer and its association with poor prognosis." (PMID 26304929, 2015). "The study showed that ARID1A is mutated in over 50 % of ovarian CCCs and pharmacological inhibition of enhancer of zeste homolog 2 (EZH2) represents a novel treatment strategy for cancers involving ARID1A mutations." (PMID 26675567, 2015). "More recently, WT EZH2 has emerged as a vulnerability in cancer associated with inactivation in the chromatin remodeling SWI/SNF complex, such as SMARCB1/INI1 mutated rhabdoid cancer and ARID1A mutated ovarian cancers." (PMID 26360609, 2015). "Cancer cells harboring EZH2 mutations were recently shown to be dependent on the EZH2 catalytic activity since their viability was severely affected by EZH2 small molecule inhibitors." (PMID 24587223, 2014). "For this reason, the overexpression of EZH2 has been correlated to the invasiveness of breast and prostate cancer and linked to various other cancer types." (PMID 24587223, 2014). "Although gene polymorphisms of EZH2 are associated with several types of cancer, the association between EZH2 variants and UCC risk and prognosis has been poorly investigated." (PMID 24691023, 2014). "A total of 233 UCC patients and 552 cancer-free controls, all of whom were from Taiwan, were analyzed for four EZH2 single-nucleotide polymorphisms (rs6950683, rs2302427, rs3757441, and rs41277434) using real-time PCR genotyping." (PMID 24691023, 2014). "Loss of PcG function is implicated in cancers, in particular, EZH2 is overexpressed in many human cancers where it silences expression of tumor suppressor genes such as the Ink4/Arf locus." (PMID 24633972, 2014). "Among PcG proteins, an emerging body of evidence suggests that overexpression, amplification, and/or somatic mutation of Ezh2 are strongly involved in many types of cancer." (PMID 25153170, 2014). "Overexpression of EZH2 has been associated with tumor progression and cancer aggressiveness in NSCLC." (PMID 24999473, 2014). "The meta analysis suggested high ID4 expression in adjacent normal samples was associated with low EZH2 whereas inverse was observed in cancer samples i.e. low ID4 but high EZH2 expression." (PMID 25115397, 2014). "The overexpression of EZH2 in human breast cancer MDA-MB-435 cells caused poor prognosis in this type of cancer." (PMID 25566531, 2014). "EZH2 is negatively regulated by miR-101 as genomic loss of miR-101 in the cancer leads to the upregulation of EZH2." (PMID 24739220, 2014). "Recently, EZH2 was linked to the aggressiveness of human cancers, including breast cancer and prostate cancer." (PMID 24691023, 2014).
cancer (continued). "The findings here reveal that EZH2 depletion by NSC745885 causes G2/M cell cycle arrest in multiple cancer cell lines." (PMID 25431950, 2014). "EZH2 is upregulated in several types of cancers and has been implicated in regulating multiple cellular processes such as proliferation, differentiation, cell cycle, apoptosis, invasion, and self-renewal." (PMID 24294976, 2013). "EZH2 protein in cancer cells has been found to be closely associated with p21waf1/cip1, pointing to EZH2 as being involved with p21waf1/cip1 regulation." (PMID 24155936, 2013). "EZH2 sequence mutations, expression levels, and copy number aberrations are correlated with the incidence and aggressiveness of various cancers and other diseases." (PMID 24367637, 2013). "Up-regulation of EZH2 plays a crucial role in malignant progression and was implicated in cancer metastasis." (PMID 23826380, 2013). "EZH2 inhibitors are equally effective in decreasing H3K27Me3 in cancer cell lines with wild type EZH2 compared with those with gain-of-function EZH2 mutations." (PMID 23494175, 2013). "DZNep has been widely employed to investigate the functions of EZH2 in diverse biological contexts including cancer, largely due to its potency to inhibit the endogenous EZH2 and associated trimethylation of H3K27 in multiple types of cells." (PMID 24345883, 2013). "Both overexpression and mutation of EZH2 are associated with the incidence and aggressiveness of various cancers." (PMID 24367637, 2013). "In many cases, high levels of EZH2 in cancer were also significantly associated with decreased E-cadherin expression and highly aggressive disease." (PMID 23940717, 2013). "Together this data suggests a causative role for elevated catalytic activity of EZH2 in the development of cancer." (PMID 24367611, 2013). "A total of 220 HCC patients and 552 cancer-free controls were analyzed for four EZH2 single-nucleotide polymorphisms (rs6950683, rs2302427, rs3757441, and rs41277434) using real-time PCR genotyping." (PMID 24040354, 2013). "An example linking cancer with a histone PTM modifying enzyme protein would be the commonly observed mutations in EZH2 HMT in certain lymphomas and myelodysplastic syndromes that reduce the catalytic activity to trimethylate H3K27." (PMID 23826629, 2013). "Recently, EZH2 has been linked to the aggressiveness of human cancers, including lymphomas, breast cancer, and prostate cancer." (PMID 24040354, 2013). "One is that EZH2 overexpression in cancer is consistently associated with poor prognosis and aggressive behavior, including invasiveness and metastatic potential." (PMID 24266940, 2013). "Although EZH2 contributes to the formation of many types of cancer, the association between EZH2 variants and HCC risk and prognosis has been poorly investigated." (PMID 24040354, 2013). "EZH2 has been identified as a transcriptional repressor and is implicated in the aggressiveness and metastasis of many types of human cancers including ESCC." (PMID 22867052, 2012). "Previous studies demonstrated that abnormal H3K27 levels or EZH2 expression were associated with cancer development and prognosis." (PMID 23057811, 2012). "Overexpression of EZH2 has been shown to cause epithelial hyperplasia in mammary glands, and to promote malignant transformation of precancerous lesions to cancers in various epithelial tissues." (PMID 23300840, 2012). "In this review, we address the current understanding of the mechanisms underlying EZH2 regulation alongside the function of EZH2 gene targets that are involved in cancer progression." (PMID 22187039, 2012). "On the other hand, EZH2 overexpression is associated with a variety of cancers and inhibition of polycomb group proteins has been suggested as a potential therapeutic strategy." (PMID 22025769, 2011).